SRGN (serglycin)
Diseases named in the same sentence as SRGN in open-access papers (continued):
Sharing a sentence is not in itself a finding about the gene and the disease.
leukemia (4 papers, 2006 to 2023). A malignant (clonal) hematologic disorder, involving hematopoietic stem cells and characterized by the presence of primitive or atypical myeloid or lymphoid cells in the bone marrow and the blood. "The peptide core of a secretory granule proteoglycan, serglycin, has been implicated in gene methylation of leukemia cells." (PMID 16959042, 2006). "In the present study we wanted to investigate the expression of syndecans, glypicans and serglycin in various types of normal lymphoid cells, as well as in different lymphoma/leukemia cell lines." (PMID 22777011, 2012).
osteosarcoma (4 papers, 2021 to 2025). A usually aggressive malignant bone-forming mesenchymal neoplasm, predominantly affecting adolescents and young adults. "According to our results, ASNS, CD70, and TRIB3 were upregulated in osteosarcoma patients, while SRGN was downregulated in osteosarcoma patients." (PMID 37732314, 2023). "The univariate Cox analysis results indicated that SRGN was a protective factor for osteosarcoma patients with hazard ratio (95% CIs) of 0.733 (0.546–0.985) (p = 0.039)." (PMID 37732314, 2023). "Our research systematically discovered and verified four immune-associated candidate hub genes (ASNS, SRGN, CD70, TRIB3) with high predictive value for diagnosing osteosarcoma by bioinformatics analysis and machine learning algorithms." (PMID 37732314, 2023). "After machine learning by SVM-RFE and LASSO regression model, four biomarkers were chosen for the diagnostic nomogram for osteosarcoma, including ASNS, CD70, SRGN, and TRIB3." (PMID 37732314, 2023). "The invasion and proliferation ability of osteosarcoma cells with upregulated Serglycin was significantly increased, and on the contrary, decreased after Serglycin knockdown." (PMID 34493692, 2021). "In conclusion, we can infer that SRGN plays a role in promoting tumorigenesis and aggressiveness in osteosarcoma." (PMID 34493692, 2021). "We found that the upregulation of SRGN expression in osteosarcoma cells promoted its proliferation, migration, and invasion." (PMID 34493692, 2021). "Consistent with the mass-spectrum analysis, quantitative PCR (qPCR) and Western blotting assays showed that the mRNA expression and protein secretion of SRGN were much higher in GCTB stromal cells than in osteosarcoma cells." (PMID 34556636, 2021). "In addition, the expression level of Serglycin (SRGN) in osteosarcoma cells was higher than that in human osteoblasts." (PMID 34493692, 2021). "However, the expression pattern and biological functions of SRGN in multiple cancer types, especially osteosarcoma remain largely unknown." (PMID 37732314, 2023). "We wondered whether SRGN also affects the JAK/STAT pathway in osteosarcoma cells." (PMID 34493692, 2021). "Also, we examined the expression level and invasiveness of this gene in osteosarcoma and found that overexpression of SRGN enhanced the invasiveness of osteosarcoma, which may be related to the malignant prognosis of osteosarcoma." (PMID 34493692, 2021). "Therefore, we selected and detected whether there was a difference in the expression level of SRGN in normal human osteoblasts and osteosarcoma cell lines." (PMID 34493692, 2021). "Our results found that osteosarcoma patients with high TRIB3 (p = 0.017) and SRGN (p = 0.010) expression levels had longer overall survival times than those with low expression." (PMID 37732314, 2023). "As a result, a total of five pivotal candidate genes (ASNS, SRGN, CD70, and TRIB3) were identified for diagnosing patients with osteosarcoma." (PMID 37732314, 2023). "The expression of SRGN was also significantly upregulated in GCTB cell lines than in other bone tumor cell lines, including chondrosarcoma, Ewing sarcoma and osteosarcoma, in the Cancer Cell Line Encyclopedia database." (PMID 34556636, 2021). "Unfortunately, whether SRGN expression is upregulated in osteosarcoma cells as in other tumors has not been reported." (PMID 34493692, 2021).
prostate carcinoma (4 papers, 2015 to 2023). A carcinoma that arises from epithelial cells of the prostate gland. "VCAN has been shown to be up-regulated in prostate cancer along with the PGs syndecan-1, perlecan, decorin, biglycan, neural/glial antigen, serglycin and lumican." (PMID 32354091, 2020). "Serglycin expression was also significantly elevated in highly aggressive and tumorigenic PC-3 prostate cancer cells." (PMID 26581653, 2015). "Other PGs may also play a role, particular those that are up-regulated in prostate cancer, such as syndecan-1, perlecan, decorin, biglycan, neural/glial antigen 2, serglycin and lumican." (PMID 32354091, 2020).
atherosclerosis (3 papers, 2021 to 2023). A disease characterized by the build-up of fatty material and calcium deposition in the arterial wall resulting in partial or complete occlusion of the arterial lumen. "Serglycin Proteoglycan Deletion in Mouse Platelets : Physiological Effects and Their Implications for Platelet Contributions to Thrombosis, Inflammation, Atherosclerosis, and Metastasis I. Progr Mol Biol Trans Sci.2010;93:235-7." (PMID 33886724, 2021). "Our biological process analysis results indicated that SRGN participated in the granzyme-mediated apoplotic signaling pathway, suggesting that it might be related to the apoptosis of immune cells in atherosclerosis, such as macrophages, T cells, and NK cells." (PMID 37089432, 2023). "SRGN and CYP1A1, may be key genes in the endothelial cell response to shear stress in atherosclerosis." (PMID 37491214, 2023).
breast tumors (3 papers, 2016 to 2023). "This points toward infiltrating immune cells being the major source of serglycin in breast tumor tissue." (PMID 35494005, 2022). "However, in vivo, we find serglycin expression to be highly related to infiltration of immune cells in the breast tumor tissue." (PMID 35494005, 2022). "To identify potential serglycin-regulated mediators of tumour growth and metastasis, we performed a global gene expression analysis (GSE67806) of breast tumour tissues from three SG+/- and three SG-/- PyMT+ mice." (PMID 27223472, 2016). "Generally, allele loss was not seen to be more abundant in patients with lower expression of SRGN, and allele gain was not more prominent amongst patients with high expression of SRGN, indicating that copy number variation does not influence SRGN expression in breast tumor tissue." (PMID 35494005, 2022).
colon carcinoma (3 papers, 2015 to 2025). "The expression of serglycin was diffuse, granular, and almost exclusively cytoplasmic in all the colon cancer cases, as well as in normal colon epithelia." (PMID 26581653, 2015). "In our pilot study, we show that serglycin is differentially expressed and secreted by breast, prostate, lung, and colon cancer cell lines." (PMID 26581653, 2015). "In the present pilot study, we examined the presence of serglycin in lung, breast, prostate, and colon cancer and evaluated its expression in cell lines and tissues." (PMID 26581653, 2015). "The expression of serglycin was found to be relatively low in colon cancer cell lines and surprisingly was higher in low aggressive CACO-2 cells as compared to more aggressive HT-29 (mutant BRAF600V→T) and DLD-1 (mutant KRAS13G→D) colon cancer cells." (PMID 26581653, 2015).
diabetic retinopathy (3 papers, 2021 to 2023). "SRGN might serve as a promising biomarker with high specificity and sensitivity in diabetic retinopathy diagnosis and progression." (PMID 37965330, 2023).
esophageal squamous cell carcinoma (3 papers, 2021 to 2025). Esophageal squamous cell carcinoma (ESCC) is a type of esophageal carcinoma (EC) that can affect any part of the esophagus, but is usually located in the upper or middle third. "This study aims to investigate the roles and mechanisms of serglycin (SRGN) proteoglycan in promoting metastasis of esophageal squamous cell carcinoma (ESCC)." (PMID 33456569, 2021).
insulinoma (3 papers, 2015 to 2016). "In contrast, serglycin-deficient mice showed increased tumour growth in the spontaneous and orthotopic insulinoma RIP-Tag2 cancer mouse model, possibly due to an improved tumour vessel functionality." (PMID 27223472, 2016). "Recently, it has been shown that serglycin is highly expressed in tumors in RIP1-Tag2 mouse model for spontaneous insulinoma formation." (PMID 26581653, 2015). "While we observed a modest expression of serglycin by beta-TC-6 insulinoma cells in vitro, very high expression was seen in material isolated from whole tumor tissue, which was comparable to the high levels observed in spleen." (PMID 25978773, 2015). "To further investigate the contribution of serglycin to tumor development, we have used the immunocompetent RIP1-Tag2 mouse model of spontaneous insulinoma formation crossed into serglycin deficient mice." (PMID 25978773, 2015).
liver cancer (3 papers, 2020 to 2025). An epithelial or non-epithelial malignant neoplasm that arises from the liver. "To confirm the role of SRGN in promoting tumor cell migration and metastasis, we quantified its mRNA and protein levels in liver cancer cell lines using qPCR and western blot." (PMID 40384866, 2025). "Serglycin (SRGN) is an important proteoglycan that regulates tumorigenesis, but its role in primary liver cancer (PLC) remains unclear." (PMID 41476965, 2025). "Significantly, various known YAP/TEAD1 targeted genes, such as BIRC5, AREG, CCND1, CTGF, and MYC, were not activated through SRGN-mediated YAP signaling in liver cancer cell lines." (PMID 40384866, 2025).
melanoma (3 papers, 2017 to 2021). A malignant, usually aggressive tumor composed of atypical, neoplastic melanocytes. "In our study, we found that the expression of SRGN was positively associated with the immune infiltrates which predicted improved overall survival of melanoma." (PMID 32370744, 2020). "So another possible explanation is that serglycin may influence inflammation of melanoma through regulating immune infiltrates." (PMID 32370744, 2020). "By LASSO Cox regression analysis, we constructed a prognosis model based on 5-mRNA (SRGN, IDO1, RARRES3, CCL4, HLA-DPB1), which has great predictive value for the overall survival of melanoma." (PMID 34805163, 2021). "Furthermore, it implies that SRGN may be a new immune target for treating melanoma." (PMID 32370744, 2020). "No reactivity for FDCSP and SRGN was detected on melanomas, thymomas or carcinomas." (PMID 28145886, 2017). "However, the role of SRGN in melanoma has not been explored before." (PMID 32370744, 2020).
triple-negative breast carcinoma (3 papers, 2017 to 2024). An invasive breast carcinoma which is negative for expression of estrogen receptor (ER), progesterone receptor (PR), and human epidermal growth factor receptor 2 (HER2). "It is shown that SRGN, due to its interaction with CD44, creates a positive loop with TGFβ2, regulating cellular migration, invasion, EMT and metastasis of the triple-negative breast cancer cell line MDA-MB-231." (PMID 38672477, 2024).
bladder cancer (2 papers, 2020 to 2021). "While CNN3, SHISA2, TMED3, SRGN were downregulated in persistently infected bladder cancer cells." (PMID 34044804, 2021).
COVID-19 (2 papers, 2023 to 2024). A disease caused by infection with severe acute respiratory syndrome coronavirus 2. "Th17 cells during COVID-19 are characterized by phenotype typical to tissue resident memory T cells also expressing the genes associated with cytolytic potential (SRGN, GZMB, and GNLY) and cytokine genes encoding IL-21, IL-17F, IL-17A, IFN-γ, and GM-CSF." (PMID 37626620, 2023). "Moreover, platelet factor 4, orosomucoids 1 and 2, as well as platelet α-granule proteins: serglycin, platelet basic protein and thrombospondin 1 were all repressed in plasma six moths after COVID-19." (PMID 39183264, 2024).
gastric cancer (2 papers, 2017 to 2024). A primary or metastatic malignant neoplasm involving the stomach. "In addition, SRGN levels in tumour tissues were closely associated with the clinical stage, and poor prognosis of patients with gastric cancer (P = 0.040)." (PMID 38862740, 2024). "IHC assays of stomach cancer tissues also showed that SRGN was mainly expressed in tumour cells, and CD44 tended to be expressed in CAFs and some lymphocytes." (PMID 38862740, 2024). "Treatment with conditioned media (CMs) of TANs from patients with locally advanced gastric cancer also upregulated SRGN levels in the gastric cancer cell lines." (PMID 38862740, 2024). "Collectively, these results suggest that TANs-derived REG4 upregulates SRGN in gastric cancer cells." (PMID 38862740, 2024). "Furthermore, tumour-associated neutrophils (TANs)-derived regenerating family member 4 (REG4) upregulates SRGN expression by activating cAMP-responsive element binding protein 1 (CREB1) in gastric cancer cells." (PMID 38862740, 2024). "We showed that SRGN knockdown or CD44 inhibition decreases IL-8 production in gastric cancer cells." (PMID 38862740, 2024). "Furthermore, we ascertained the modulation of SRGN expression in the gastric cancer microenvironment." (PMID 38862740, 2024). "Bioinformatics analyses also showed a positive correlation between SRGN and CREB1 in gastric cancer (P < 0.001)." (PMID 38862740, 2024). "Analyses using TCGA database showed that SRGN levels in gastric cancer tissues were significantly higher than those in adjacent normal tissues (P < 0.010), and assays with clinical specimens also obtained similar results." (PMID 38862740, 2024).
head and neck squamous cell carcinoma (2 papers, 2023 to 2025). A squamous cell carcinoma that arises from any of the following anatomic sites: lip and oral cavity, nasal cavity, paranasal sinuses, pharynx, larynx, and salivary glands. "Under hypoxic conditions, CAFs secrete serglycin (SRGN), which facilitates the nuclear accumulation of β-catenin in head and neck squamous cell carcinoma (HNSCC), thereby activating Wnt/β-catenin signaling and promoting cellular stemness and drug resistance." (PMID 41583435, 2025).
metastatic disease (2 papers, 2016 to 2020). "Our results suggest that serglycin and serglycin-dependent mediators are potential drug targets to prevent metastatic disease/dissemination of cancer." (PMID 27223472, 2016).
prostate adenocarcinoma (2 papers, 2015 to 2020). "Two low-grade (Gleason score 4), 3 moderate-grade (Gleason score 6), and 5 high-grade prostate adenocarcinomas (Gleason score 10) were examined for serglycin expression." (PMID 26581653, 2015).
psoriasis (2 papers, 2024 to 2025). An autoimmune condition characterized by red, well-delineated plaques with silvery scales that are usually on the extensor surfaces and scalp. "Correspondingly, cytotoxic mediators such as PRF1, GZMA, SRGN, and NKG7 were upregulated, paralleling signatures seen in αβ T cells in psoriasis." (PMID 41181116, 2025). "The list of differentially expressed proteins also includes immune-related molecules, such as in TPM4 [FC = 2.2; p = 0.009], Serglycin (SRGN) [FC = 0.08; p = 0.03] or antioxidant proteins, such as GSTP1 [FC = 5.3; p = 0.03] in psoriasis." (PMID 39062477, 2024).
schizophrenia (2 papers, 2024). A major psychotic disorder characterized by abnormalities in the perception or expression of reality. "In the neurological system, SRGN was shown to regulate the progression of schizophrenia, Alzheimer’s disease and spine cord injury repair." (PMID 38287411, 2024).
Stroke (2 papers, 2024 to 2025). Sudden impairment of blood flow to a part of the brain due to occlusion or rupture of an artery to the brain. "We revealed that SRGN amplified post-stroke neuroinflammation via promoting microglial proinflammatory activation in MCAO mice, while Srgn deletion alleviated microglia-mediated neuroinflammation." (PMID 38287411, 2024). "Although the molecular pathways regulating microglia/ECM interplay have not been fully elucidated, the interaction between the ECM protein serglycin (SRGN) and CD44 expressed by microglia has been recently described in an experimental model of stroke." (PMID 40943148, 2025). "Thus, targeting SRGN might provide new strategies for alleviating post-stroke brain injury." (PMID 38287411, 2024). "Thus, by targeting SRGN and its interaction with CD44, we can gain valuable insights into treatment of stroke." (PMID 38287411, 2024). "However, the expression of SRGN in stroke and stroke-related microglia has not been detected." (PMID 38287411, 2024). "However, the interplay between SRGN and CD44 has not been explored in the context of stroke." (PMID 38287411, 2024).
Autoimmunity (1 paper, 2020). The occurrence of an immune reaction against the organism's own cells or tissues. "Transcriptome group 3 (ACVRL1, CD93, CEBPB, NINJ1, SRGN) encodes preferentially for proteins related to autoimmunity." (PMID 32325790, 2020).
bacterial sepsis (1 paper, 2025). "The eight differentially expressed genes (DEGs) as key diagnostic markers for bacterial sepsis: FTH1, B2M, NAMPT, KLF6, SRGN, S100A6, S100A9, and S100A8." (PMID 41303672, 2025).
bone tumor (1 paper, 2021). "Our data also showed the upregulation of SRGN in GCTB in comparison of other bone tumors and healthy control." (PMID 34556636, 2021).
brain ischemia (1 paper, 2024). Diminished or absent blood supply to the brain caused by obstruction (thrombosis or embolism) of an artery resulting in neurologic damage. "This study provides the first evidence that secretory protein SRGN was remarkably elevated after brain ischemia in mice." (PMID 38287411, 2024).
brain tumors (1 paper, 2017). "Although several recent studies have demonstrated the emerging role of serglycin in tumorigenesis not much information is available on the expression and distribution of this proteoglycans in brain tumors." (PMID 28445977, 2017).
cerebral amyloid angiopathy (1 paper, 2023). "SRGN and SDC4 were over-expressed in most of the areas, and immunohistochemistry revealed the presence of SRGN in all three types of AD lesion: neuritic plaques, cerebral amyloid angiopathy, and neurofibrillary pre-tangles and tangles." (PMID 37762527, 2023).
cervical cancer (1 paper, 2024). A primary or metastatic malignant neoplasm involving the cervix. "However, the function of SRGN and HIST1H1C has not been explored in cervical cancer." (PMID 38346944, 2024).
Cirrhosis (1 paper, 2022). A chronic disorder of the liver in which liver tissue becomes scarred and is partially replaced by regenerative nodules and fibrotic tissue resulting in loss of liver function. "We could observe that the A1 subtype-related markers (FKBP5, GBP2, PSMB8, and SRGN) were remarkably elevated in HE samples compared to healthy control samples and cirrhosis samples." (PMID 36424620, 2022).
Cognitive impairment (1 paper, 2021). Abnormal cognition is characterized by deficits in thinking, reasoning, or remembering. "Notably, SRGN was the most consistently downregulated gene across all cortical regions examined and one of the genes strongly associated with cognitive impairment in subjects with SZ." (PMID 33070392, 2021). "The CSPG/HSPG serglycin (SRGN), hyaluronan receptor CD44 and insulin‐like growth factor‐binding protein 3 (IGFBP3) were among the most consistently downregulated genes associated with both mild and severe cognitive impairment in subjects with SZ." (PMID 33070392, 2021).
dendritic cell sarcoma (1 paper, 2017). A sarcoma that involves the dendritic cell. "SRGN, together with CD21 and CD35, was negative in all non-FDC-S tumors; FDCSP, expressed by one case of SNHP, one case of SS and one case of interdigitating dendritic cell sarcoma, still showed a better performance than other widely used FDC markers." (PMID 28145886, 2017).